SHH (sonic hedgehog signaling molecule)
Diseases named in the same sentence as SHH in open-access papers (continued):
Sharing a sentence is not in itself a finding about the gene and the disease.
cancer (continued). "Many studies have investigated the SHH pathway as a cancer drug target using cyclopamine, vismodegib, itraconazole, and other SHH pathway modulators." (PMID 31401336, 2019). "In concordance with our preclinical data, research in mouse models of other human cancers, in which the activation of the SHH pathway is also ligand dependent, has revealed that the inhibition of this pathway (e.g. using vismodegib) is protumourigenic." (PMID 30645190, 2019). "Recently, several pieces of evidence also imply that ATO attenuates the cancer stem cells (CSCs) population with the involvement of SHH pathway, Notch pathway, and TGF-β pathway." (PMID 31186405, 2019). "Our results also indicated that GZ17-6.02 is a potent inhibitor of the SHH pathway, that in turn, inhibited self-renewal of cancer cells." (PMID 30899425, 2019). "The expression levels of SHH signaling proteins varied among the cancer cell lines and normal cell lines." (PMID 31783569, 2019). "The dysfunction of SHH pathway is involved in a variety of diseases, including cancer, birth defects, and other diseases." (PMID 31898580, 2019). "In the cancer parenchyma, SHH was strongly expressed in the cytoplasm of cancer cells in ED type: Moderate (+2), five patients; marked (+3), 10 patients, and more strongly in the cancer nests at the front line of invasion." (PMID 31744214, 2019). "A reduction in CAFs in GEMMs of pancreatic tumors harboring a genetic deletion of SHH in the cancer cells also resulted in more aggressive tumors with increased cancer cell proliferation, which was possibly mediated by an enhanced tumor vascularity." (PMID 29686035, 2018). "SHH, a regulator of vertebrate organogenesis, controls the proliferation of several types of stem cells and cancers." (PMID 28708091, 2017). "In all these cases, aberrant SHH signaling activation upregulates cancer cell proliferation, maintains cancer stem cells and, eventually in some cases, enhance their metastatic potential." (PMID 29615561, 2017). "There are pathways known for differentiation of taste bud cells such as sonic hedgehog (SHH) and notch pathways which are modulated during cancer." (PMID 28337150, 2017). "Aberrant activation of SHH/GLI pathway in the adult leads to cellular proliferation manifests as cancer." (PMID 28446712, 2017). "SHH/GLI1 signaling pathway has been characterized as a NF-κB target pathway that promotes NF-κB-mediated apoptosis resistance in cancers." (PMID 28446712, 2017). "For example, Sonic Hedgehog (SHH), the most common and understood one, is crucial in embryo development, cancer progression, and body patterning." (PMID 27043642, 2016). "The role of SHh pathway in cancer development is suspected to be via the transformation of adult stem cells into cancer stem cells." (PMID 27533453, 2016). "One of the best studied oncogenic signaling pathways is the SHH pathway which was already analyzed in combination with cilia in cancer cells." (PMID 27293550, 2016). "Overexpression of Fbxl17 in SHH subgroups provides a therapeutic window to selectively target cancer cells." (PMID 27234298, 2016). "There are clinical reports on abnormal activation of the SHH signaling pathway in different types of cancer." (PMID 27043642, 2016). "The stem cell biomarkers CD133, ALDH-1 as well as SHH and its downstream effector Gli-1 are involved in cancer stem cell self-renewal, clonogenicity, tumorigenicity, metastasis and drug resistance of numerous solid cancers, including PDAC." (PMID 27281617, 2016). "Sonic hedgehog (SHH) and its signaling have been identified in several human cancers, and increased levels of its expression appear to correlate with disease progression and metastasis." (PMID 27007126, 2016). "De-regulation of sonic Hedgehog (SHH) and EGFR dependent signaling pathways have been implicated in about one third of all human cancers." (PMID 26571415, 2015).
cancer (continued). "Aberrant activation of sonic Hegdehog (SHH) signaling has been found to disrupt cellular differentiation in many human cancers and to increase proliferation." (PMID 26571415, 2015). "Several studies have identified the key signaling pathways that play crucial roles in the growth and survival of stem cells from both normal and cancer tissue, such as Wnt/β-catenin, Notch, SHH and BMP signaling." (PMID 26457069, 2015). "More importantly, in relation to cancer, the SHH/Gli pathway is known to promote self-renewal of CSCs by transcriptionally regulating expression of various genes." (PMID 26317547, 2015). "It has been previously reported that YangZheng XiaoJi also impacts on the focal adhesion kinase (FAK), the AKT and sonic hedgehog (SHH) pathways in cancer cells and vascular endothelial cells." (PMID 26310485, 2015). "Cyclopamine for example, acts at the level of SHH signaling and is effective in reducing the viability of cancer cells by blocking activation of the SHH response pathway and abnormal cell growth." (PMID 27386018, 2015). "Constitutive activation of SHH signaling and SHH-dependent proliferation have been found in a variety of cancers including lung, esophagus, stomach and pancreas." (PMID 23835807, 2013). "Taken together, these data support the view that SHH expression in SHH-high cancer cells is a survival selective advantage that prevents CDON-induced apoptosis." (PMID 23940460, 2013). "SHH signaling is indeed a major focus for drug development, since SHH and its downstream signaling have been believed to be frequently deregulated in cancer." (PMID 23940460, 2013). "Conversely, our present data and previous reports support the view that a fraction of tumors from various cancer types shows expression of SHH." (PMID 23940460, 2013). "Recent evidence from in vitro and in vivo studies has demonstrated that aberrant reactivation of the Sonic Hedgehog (SHH) signaling pathway regulates genes that promote cellular proliferation in various human cancer stem cells (CSCs)." (PMID 22087285, 2011). "The signal pathways such as the Cell Cycle, MAPK, SHH, WNT, PRC2, Notch, PTEN and TGFβ involved in the hESC fate determination were also strongly associated with cancer genesis, progression and prognosis." (PMID 22041030, 2011). "We have recently shown that the subcellular localization and transcriptional activity of GLI3 is regulated by PP2A activity and the MID1-α4 ubiquitin ligase complex in several cancer cell lines with autonomously activated SHH-signaling." (PMID 19829694, 2009). "In addition, the covalent cyclin-dependent kinase 7 (CDK7) inhibitor THZ1 inhibits cancer stemness by disrupting SHH signaling." (PMID 40635786, 2025). "SHH inhibitors are one of the groups being investigated for use in cancer therapy." (PMID 40003568, 2025). "Cancer stem cell self-renewal is under control by the SHH/SMO/GLI signaling system." (PMID 39900571, 2025). "The combination of curcumin with compounds like AZD5363, AZD8542, and resveratrol exhibits synergistic effects, suppressing both the PI3K/AKT and SHH pathways, targeting multiple survival mechanisms in cancer cells and potentially enhancing cell death while reducing treatment resistance." (PMID 40227413, 2025). "The SHH protein, which plays a key role in embryogenesis, is also involved in promoting growth, metastasis and the resistance of cancer tumours to treatment with cytostatics and regulates the metabolism of cancer stem cells." (PMID 40003568, 2025). "This multifaceted inhibition of the SHH/GLI1 pathway translates into tangible anti-cancer effects, including suppressed cell proliferation, colony formation, and migration, and increased apoptosis, partially mediated through the mitochondrial pathway, as evidenced by an increased Bax/Bcl2 ratio." (PMID 40227413, 2025).
cancer (continued). "The preferential activation of SHH signalling by PARD3 in stem like cancer cells could contribute to the maintenance of their stem-like state, promoting self-renewal and inhibiting differentiation." (PMID 38317186, 2024). "Finally, SHH, although meeting fewer gene prioritization criteria, is a key signaling factor in both genitourinary development and cancer." (PMID 39639036, 2024). "In addition, the phosphorylation of aPKC was significantly correlated with the expression of Gli1, PARD3 and Sox2 (R > 0.4), emphasizing the important role of aPKC in mediating PARD3, SHH signalling and cancer stemness." (PMID 38317186, 2024). "In cancer, such paracrine SHH signaling promotes the outgrowth of the surrounding stroma." (PMID 37832945, 2024). "Understanding the SHH pathway’s role in EC contributes to our growing knowledge of this cancer and may pave the way for more effective treatment strategies in the future." (PMID 39408773, 2024). "The SHH signalling pathway plays a crucial role in the development and growth of various cancers." (PMID 39568072, 2024). "In particular, we focused on the SHH signaling pathway that regulates cancer stem cells." (PMID 36797277, 2023). "Reports regarding SHH protein immunoreactivity in other types of cancer are inconsistent." (PMID 37964226, 2023). "On the other hand, in grade G1 of ccRCC, SHH had the highest expression in cancer cells, which might imply its role in the early carcinogenesis and impaired signalling of subsequent genes involved in this pathway." (PMID 37240278, 2023). "However, although we can rely on SHH signalling proteins as biomarkers not only in ccRCC but in a pan-cancer model as well, we should be aware that treatment modalities require verification by further in vivo studies." (PMID 37240278, 2023). "Dysregulation and activation of the SHH signaling cascade is implicated in several cancers, but to date not studied in detail in PNSTs34." (PMID 37164978, 2023). "Vismodegib (GDC-0449) is an FDA-approved SMO inhibitor targeting SHH-driven cancers." (PMID 36683064, 2023). "In cancer, a dysregulated NF-κB pathway leads to aberrant SHH expression." (PMID 38004606, 2023). "This study showed that the SHH protein promoted PCa bone metastasis, which was consistent with the previous study that the SHH paracrine signaling was found to be involved in the regulation of cancer cells, osteoblasts, and osteoclasts." (PMID 35285760, 2022). "Cancer cells secrete sonic Hedgehog (SHH) to promote their proliferation and survival." (PMID 35327484, 2022). "However, targeting cancer stem cells by inhibiting the SHH pathwayhas been found to improve drug resistance." (PMID 36034794, 2022). "The sonic hedgehog (SHH) signaling pathway has been intensively studied in cancers." (PMID 36034794, 2022). "As we demonstrate that SHH exerts a control on cell division during the time of mitosis in cancer cells and in NSC, therapeutic limitations may exist." (PMID 35831316, 2022). "Furthermore, the N-terminal product of SHh (ShhN) has been shown to be overexpressed in cancer and thus can be recognized as a promising target that merits further consideration." (PMID 36517618, 2022). "Since it has been reported that sonic hedgehog (SHH) increases cancer stemness." (PMID 35047127, 2022). "Expression of Sonic is up-regulated in the surrounding pancreatic fibroblasts which also demonstrates increased VEGF expression, thus alluding to the role of SHH in angiogenesis, and highlighting the intimate role of SHH pathway in the regulation of cancer cells and the surrounding TME." (PMID 36428556, 2022). "The activation of SHH signaling is also a feature of cancer stem cells." (PMID 35047127, 2022). "Several other SHH/HH signalling inhibitors were approved or were under experimental investigation as cancer treatments including the GLI inhibitors arsenic trioxide and GANT-61, the Shh palmitoylation inhibitor RU-SKI 43, and the monoclonal antibodies that block SHH binding/function." (PMID 34576017, 2021).
cancer (continued). "Here, we have identified a relationship between NKX6-1 expression and SHH signaling activation in cancer cells and we therefore propose that SHH inhibition may represent a feasible strategy for the treatment of NKX6-1high LMS patients." (PMID 33906647, 2021). "Based on the high anti-cancer activity of the SHH pathway-inhibitor ACVR1 in preclinical studies, a variety of clinically active small molecule inhibitors were developed including saridegib, erismodegib, or vismodegib, the latter showing promising clinical responses in SHH-driven MB." (PMID 34073340, 2021). "Since the deletion of SHH expression might impair CAFs activation signaling, what is the impact on malignant progression if SHH expression is removed from cancer cells?" (PMID 33614646, 2021). "However, some studies have suggested that abnormal expression of SHH is related to the formation of cancer stem cells through interacting with TGF-β1, which results in bladder tumorigenesis, even resistance to chemotherapy and radiotherapy." (PMID 35004540, 2021). "Furthermore, knockdown of SUFU expression partially rescued the ROC1 knockdown-suppressed SHH activity as well as cancer cell growth inhibition." (PMID 33499884, 2021). "Therefore, a better understanding of the specific mechanism of SHH signaling pathway activation will help to facilitate anti-cancer drugs." (PMID 33391411, 2021). "Combined use of SHH signaling inhibitors and chemotherapy/radiation therapy/immunotherapy could be key in targeting cancer stem cells." (PMID 31979397, 2020). "The GLi and SHH are part of the hedgehog signaling pathway that plays an essential role in the differentiation, growth, tissue patterning and cell maintenance of various cancers." (PMID 32523911, 2020). "There is a new body of evidence that HOTAIR is also overexpressed in a number of cancers, which suggests that HOTAIR may play a role in SHH dysregulation in cancer." (PMID 33303026, 2020). "In ER-positive breast cancer cells remodeling of the cancer microenvironment could facilitate an antioxidant response to SHH signaling to enhance the CSC activity." (PMID 32962123, 2020). "Better understanding of these mechanisms could help us better target the SHH pathway against cancer." (PMID 31979397, 2020). "Aberrant activation of the Sonic Hedgehog (SHH) gene is observed in various cancers." (PMID 32341755, 2020). "Moreover, aberrant activation of SHH signaling occurs in cancers of skin, brain, liver, gallbladder, pancreas, stomach, colon, breast, lung, prostate, and hematological malignancies." (PMID 31979397, 2020). "Moreover, aberrant activation of SHH signaling occurs in cancers of the skin, brain, liver, gallbladder, pancreas, stomach, colon, breast, lung, prostate, and hematological malignancies." (PMID 31979397, 2020). "Previous studies have focused on the crosstalk between SHH-GLI signaling and several oncogenic pathways including MAPKs, PI3K/AKT/mTOR, and TGFβ/SMAD signaling pathways, and implicated the strategy of targeting SHH-GLI and MEK1/2 for the therapy of cancers." (PMID 32670287, 2020). "There may be cross-talk between ER- and SHH-signaling pathways facilitating the invasiveness of ER-positive cancer cells." (PMID 32962123, 2020). "Further research will be necessary to establish whether in this context Tbx1, might trigger an autoregulatory loop (Tbx1-WNT-Sox9-Tbx1) that reduces the dependence of BCC cancer cells from SHH signaling." (PMID 31963474, 2020). "As mentioned, the SHH pathway is essential in the development of cancer." (PMID 30899425, 2019). "However, a large concentration of CD68 was observed at the site close to the cancer parenchyma where SHH expression was strong." (PMID 31744214, 2019). "Considering the characteristics of their distribution and shape, CD11b-positive cells in OSCC may represent TAMs, and some CD11b-positive cells may have been recruited by SHH signaling in the cancer parenchyma." (PMID 31744214, 2019).
cancer (continued). "NF-κB positively regulates SHH expression in a variety of cancer types, including BC." (PMID 31027259, 2019). "The SHh pathway is considered to play a crucial role in tumorigenesis and cancer." (PMID 31616295, 2019). "Oxy210 significantly inhibited the expression of SHH mRNA in A549 cells, suggesting that Oxy210 could block paracrine Hh signaling by targeting both cancer cells and stromal cells." (PMID 31652618, 2019). "Autocrine SHH signaling depends on secretion of SHH ligands by the cancer parenchyma." (PMID 31744214, 2019). "The histological comparison between ED type and EX type provides authentic evidence for the involvement of the SHH pathway in the development of cancer via differentiation into various kinds of cells in the cancer stroma, such as macrophages, fibroblasts, and endothelial cells." (PMID 31744214, 2019). "The expression of SHH and PTCH was higher in ED-type cancer parenchyma than in EX-type parenchyma, suggesting that SHH signaling may be involved in not only cancer growth but also cancer invasion." (PMID 31744214, 2019). "First, we demonstrated autocrine expression of SHH in OSCC cancer parenchyma." (PMID 31744214, 2019). "Therefore, hedgehog pathway signalling has emerged as a legitimate targetable pathway in a number of cancers including SHH-driven MB." (PMID 31362788, 2019). "In conclusion, given all the findings we observed from OSCC of ED type and EX type, the SHH pathway may participate in the processes of tumorigenesis and cancer development." (PMID 31744214, 2019). "The upregulation was completely abrogated in the presence of the SHH-neutralizing antibody, suggesting that the SHH protein endogenously expressed in and secreted from cancer cells under hypoxic conditions significantly evoked the Sonic hedgehog signaling in fibroblasts in a paracrine manner." (PMID 29535824, 2018). "Besides, overexpressed genes were identified to involve in other pathways, including FGF signaling, SHH signaling, and that are commonly found in various types of cancers." (PMID 30363662, 2018). "By contrast, hedgehog acyltransferase (HHAT) gene expression is associated with cell growth and is suggested to play a role in cancer by promoting the N-terminal palmitoylation of sonic hedgehog (SHH), which is required for proper SHH signaling involved in the control of cell growth." (PMID 30338036, 2018). "Moreover, it is well documented that Gli-1 mediates the mitogen effects of the SHH pathway in the regulation of growth of proliferating normal cells as well as several cancer cells." (PMID 29867331, 2018). "Moreover, activation Hh signaling by N-SHH, a recombinant SHH peptide, subdued autophagy level and partially rescued cancer cells from Hh inhibition-induced cytotoxicity, suggesting the role of autophagic cell death." (PMID 30081498, 2018). "This process is regulated by a number of converging signaling cascades, including the Sonic Hedgehog (SHh) pathway, and confers critical traits required for seeding metastasis and developing stem cell properties that allow new cancer cell colonies to be launched." (PMID 29416661, 2018). "Because SHH overexpression is a poor prognosis marker for HNSCC the development of SHH inhibitors may improve the cancer therapy of HNSCC." (PMID 28708091, 2017). "Furthermore, an SHH inhibitor reduced viability and promoted apoptosis in the cancer cell line HCT-116." (PMID 26716648, 2016). "Based on these observations, blocking SHH signaling is a popular strategy in cancer therapy." (PMID 27043642, 2016). "Importantly, several studies have suggested cancer cells acquire stemness and drug resistance properties by the activation of the Wnt/β-catenin, Notch and SHH pathways." (PMID 26457069, 2015).